FBN1 (fibrillin 1)
Diseases named in the same sentence as FBN1 in open-access papers (continued):
Sharing a sentence is not in itself a finding about the gene and the disease.
Marfan syndrome (continued). "We conclude that the downregulation of fibulin-1 and/or of decorin in AAD patients could be an alternative molecular mechanism—opposed to a mutation in fibrillin-1 as seen in patients suffering from Marfan syndrome—leading to the same or similar phenotype." (PMID 19652764, 2009). "Marfan syndrome, a disorder of connective tissue architecture with prominent manifestations in the skeletal, ocular and cardiovascular systems, is caused by mutations in the fibrillin-1 gene or by loss of function mutations in TGFβ receptor I or II." (PMID 19742316, 2009). "Marfan syndrome (MFS) results from pathogenic FBN1 variants and is typically inherited in an autosomal dominant pattern with variable expressivity and pleiotropy." (PMID 41511357, 2026). "Marfan syndrome (MFS) is an autosomal dominant connective tissue disorder caused by pathogenic variants in the fibrillin-1 (FBN1) gene on Chromosome 15q21.1." (PMID 41815795, 2026). "Although fibrillin-1 mutations affect all segments of the aorta, disease first manifests at the aortic root and proximal ascending aorta, the region most susceptible to dissection and rupture in Marfan syndrome, again likely accelerated in part by proximal pulse pressure augmentation." (PMID 39830801, 2025). "FBN1 encodes fibrillin-1, a protein associated with Marfan syndrome (MFS) and connective tissue elasticity, often accompanied by high myopia." (PMID 41259386, 2025). "MVP, in addition to other cardiovascular abnormalities such as aortic dilatation, also occurs in patients with Marfan syndrome (MFS) resulting from pathogenic FBN1 variants." (PMID 40392604, 2025). "Pathogenic variants lead to the development of FBN1-associated syndromes which comprise a broad host of phenotypes, and more commonly, Marfan syndrome (MFS)." (PMID 40496209, 2025). "Marfan syndrome (MFS) is a genetic connective tissue disorder inherited in an autosomal dominant manner, primarily caused by mutations in the fibrillin-1 (FBN1) gene." (PMID 40923051, 2025). "Marfan syndrome (MFS) is an autosomal dominant genetic disorder of the connective tissues caused by mutations in the fibrillin-1 (FBN1) gene." (PMID 39817456, 2025). "Marfan syndrome (MFS) is a genetic disorder caused by mutations in fibrillin-1(FBN1), which encodes FBN1, a key structural component of the extracellular matrix." (PMID 41040364, 2025). "Fibrillin 1 gene (Fbn1) mutations cause Marfan syndrome (MFS), triggering life-threatening aortic complications and multi-organ effects." (PMID 40349485, 2025). "Finally, as well as Marfan Syndrome, other fibrillinopathies might carry variants in the FBN1 gene, and a differential diagnosis should frequently be considered." (PMID 40123664, 2025). "Marfan syndrome (MFS) is a multisystem disorder caused by mutations in the FBN1 gene and, to a lesser extent, in TGFBR2." (PMID 40565081, 2025). "Marfan syndrome (OMIM #154700) (MFS) is a genetic disease characterized by mutations in the FBN1 gene." (PMID 40695874, 2025). "Marfan syndrome (MFS) is an autosomal dominant hereditary connective tissue disorder (HCTD) caused by mutation in FBN1." (PMID 40075421, 2025). "The extensive size and multi-exon structure and the tissue-restricted expression of the associated gene FBN1 challenge the genetic diagnosis of Marfan Syndrome (MFS)." (PMID 41256009, 2025). "Thoracic aortic aneurysm (TAA) is the major cardiovascular manifestation of Marfan Syndrome (MFS), a connective tissue disorder caused by mutations in fibrillin-1." (PMID 40550200, 2025). "Whilst the aetiology of spontaneous EL is broad, the predominant cause is an autosomal dominant variant in FBN1 in 87.3% of cases, most commonly manifested as Marfan syndrome (MFS) (OMIM # 154700)." (PMID 39766898, 2024). "Marfan syndrome (MFS) is an autosomal dominant connective tissue disease with wide clinical heterogeneity, and mainly caused by pathogenic variants in fibrillin-1 (FBN1)." (PMID 38773661, 2024).
Marfan syndrome (continued). "Marfan syndrome (MFS) is a disease resulting from a mutation in Fibrillin-1 (FBN1), a key connective tissue ECM protein." (PMID 39593756, 2024). "Mutations in fibrillin-1 (FBN1) are known to be associated with Marfan syndrome (MFS), an autosomal dominant connective tissue disorder." (PMID 38317175, 2024). "Pathogenic variants of FBN1 usually cause the phenotype of Marfan syndrome (MFS), the most common fibrillinopathy." (PMID 37972149, 2024). "Marfan syndrome (MFS) is a systemic connective tissue disorder stemming from mutations in the gene encoding Fibrillin-1 (Fbn1), a key extracellular matrix glycoprotein." (PMID 39684412, 2024). "To address this question, we analyzed the localization and distribution of EMILINs, along with fibrillin-1, in the skin of Marfan syndrome (MFS) patients harboring various confirmed FBN1 mutations, at ages 20, 48, and 58 years." (PMID 39639116, 2024). "Mutations in the FBN1 gene can result in two opposite skeletal features: Marfan syndrome (MFS, OMIM #154700), characterized by tall stature and arachnodactyly, and acromelic dysplasia, characterized by short stature and brachydactyly." (PMID 39077065, 2024). "Marfan syndrome (MFS) is a heritable connective tissue disorder caused by a mutation of the fibrillin-1 gene (FBN1)." (PMID 39073692, 2024). "The mgΔlpn mouse strain carries a Fbn1 variant that replicates in mice the classic phenotypic traits of patients with Marfan syndrome (MFS)." (PMID 38545339, 2024). "Marfan syndrome (MFS) is a type 1 fibrillinopathy, a connective tissue disease caused by FBN1 pathogenic variants." (PMID 38700693, 2024). "Marfan Syndrome (MFS) is a connective tissue disorder caused by mutations in the fibrillin-1 (Fbn1) gene." (PMID 38461168, 2024). "Marfan syndrome (MFS) is an autosomal-dominant multisystem connective tissue disorder that is based on mutations in the FBN1 gene and variably affects different organs, including the heart." (PMID 37892098, 2023). "Marfan syndrome (MFS) is a heritable connective tissue disorder that is caused by a mutation of the FBN1 gene." (PMID 37750108, 2023). "Mutations in the fibrillin-1 gene (FBN1) are linked to Marfan syndrome (MFS), a systemic connective tissue disorder that, besides other heterogeneous symptoms, usually manifests in life-threatening aortic complications." (PMID 37108724, 2023). "Marfan syndrome (MFS) is an autosomal dominant inherited disease of connective tissue caused by a variation in the fibrillin-1-gene (FBN-1) in 90% of the cases." (PMID 37160466, 2023). "FBN1 gene mutations predispose Marfan syndrome (MFS) patients to TAA at a young age and premature death from catastrophic aneurysm rupture or dissection." (PMID 37511460, 2023). "Marfan syndrome (MFS) is an autosomal dominant multiorgan disease usually related to FBN1 gene pathogenic variants." (PMID 37109238, 2023). "Intronic variants in FBN1 were also proven to cause intron retention by RNA-Seq in Marfan syndrome (MFS; OMIM: #154700) family." (PMID 36672937, 2023). "Marfan syndrome (MFS) is an autosomal dominant connective tissue disorder caused by variants in the extracellular microfibril fibrillin (FBN1) gene." (PMID 37397156, 2023). "The most frequent syndromic disease associated with MVP is Marfan syndrome (MFS), a genetic disorder that affects the connective tissue caused by fibrillin-1 (FBN1) mutations in its most common form." (PMID 36545732, 2023). "Marfan syndrome (MFS) is a rare genetic disorder of the connective tissue caused by mutations in the Fibrillin-1 (FBN1) protein, which is encoded by the FBN1 gene." (PMID 37397303, 2023). "Marfan syndrome (MFS) is an autosomal dominant connective tissue disorder caused by mutation in fibrillin-1 (FBN1)." (PMID 36972239, 2023). "Marfan syndrome (MFS) is a connective tissue disorder caused by FBN1 gene mutations leading to TGF-β signaling hyperactivation, vascular wall weakness, and thoracic aortic aneurysms (TAAs)." (PMID 37894814, 2023).
Marfan syndrome (continued). "Marfan syndrome (MFS) is associated with mutations in the protein fibrillin-1 (FBN1), which affects the integrity of connective tissue elastic fibers." (PMID 36936176, 2023). "Marfan syndrome (MFS) is an autosomal-dominant connective tissue disorder, most commonly caused by missense mutations in the FBN1 gene." (PMID 35547588, 2022). "Marfan syndrome (MFS) is an inherited connective tissue disorder with an incidence of 2–3 per 10,000 individuals, caused by mutations in the FBN1 gene." (PMID 36061830, 2022). "Thoracic aortic aneurysm (TAA), leading to acute medial dissection (TAAD), is the most life-threatening manifestation of Marfan syndrome (MFS), a multi-system connective tissue disorder caused by mutations in fibrillin-1." (PMID 35053276, 2022). "Marfan syndrome (MFS) is one of the most common hereditary connective tissue disorders with a prevalence of 20 per 100.000, caused by a mutation in the fibrillin-1 gene." (PMID 36712236, 2022). "It is well-known that increasing levels of TGF-β1 are associated with Marfan syndrome (MFS) caused by FBN1 mutation and subsequent defects in the signaling system." (PMID 36148051, 2022). "Marfan syndrome (MFS) an inherited disorder caused by FBN1 gene variants, is well known to cause lethal aortic aneurysm and dissections at a relatively young age." (PMID 35957784, 2022). "Mutations in the human fibrillin-1 gene (FBN1) cause Marfan syndrome (MFS; Online Mendelian Inheritance in Man [OMIM] #154700, prevalence 1/5000 to 1/10,000)." (PMID 36291539, 2022). "LDS and SGS have many similarities common to fibrillinopathies, specifically Marfan syndrome (MFS), which is caused by mutations in FBN1." (PMID 35378950, 2022). "Marfan Syndrome (MFS) is an autosomal dominant systemic disorder caused by mutations in the extracellular matrix protein: fibrillin-1 (FBN1)." (PMID 35055593, 2022). "Marfan syndrome (MFS) is a life-threatening autosomal dominant genetic disorder of connective tissue caused by the pathogenic mutation of FBN1." (PMID 36292727, 2022). "Marfan syndrome (MFS; 154,700) is a genetic disorder with autosomal dominant heritage caused by pathological variants in the fibrillin-1 gene (FBN1; 134,797)." (PMID 35248143, 2022). "Additional murine models for Marfan syndrome include the Fbn1C1039G/C1039G model, in which mice have a missense mutation causing normal Fbn1 expression but aberrant fiber formation, and the Fbn1GT−8/GT−8 model, where Fibrillin-1 is truncated and has four-fold reduced expression." (PMID 35492343, 2022). "Further evidence about the role of MFAP4 in elastic tissues comes from studies on Marfan syndrome (MFS), a rare genetic disorder of the connective tissue caused by mutations in the fibrillin-1 gene." (PMID 35805199, 2022). "Heterozygous mutations in the gene for ECM protein Fibrillin-1, FBN1, cause Marfan syndrome (MFS1; MIM 154700) in patients, an autosomal dominant disorder with wide clinical variability affecting the cardiovascular, ocular and skeletal systems." (PMID 35492343, 2022). "Marfan syndrome (MFS) is an autosomal dominant connective tissue disorder, which is caused by mutations in the fibrillin-1 (FBN-1) gene." (PMID 36279189, 2022). "Marfan syndrome (MFS) is the most common genetic form of thoracic aortic aneurysm disease, caused by pathogenic variants of the microfibrillar protein fibrillin-1, an ECM component acting as scaffold for elastin, as well as contributing to TGF-β signaling." (PMID 35224059, 2022). "Fibrillin-1 insufficiency in Marfan syndrome (MFS) leads to structural weakness, which causes various tissue disorders, including cardiovascular and periodontal diseases." (PMID 34445604, 2021). "Marfan syndrome (MFS) is a connective tissue disorder caused by mutations in the Fibrillin-1 gene (FBN1)." (PMID 34895303, 2021). "Marfan syndrome (MFS) is a heritable connective tissue disorder (HCTD) caused by pathogenic variants in FBN1 that frequently occur de novo." (PMID 33414558, 2021).
Marfan syndrome (continued). "Marfan syndrome (MFS) is an AD inherited mutation in the FBN1 gene on chromosome 15 that encodes for fibrillin-147, leading to excessive signaling and activation of TBF-beta." (PMID 34501218, 2021). "Indeed, after the exclusion of Marfan syndrome (more frequently associated with musculoskeletal involvement) through the assessment of Marfan Systemic Score and/or FBN1 analysis, clinicians should consider collagenopathy in its different, and perhaps atypical, forms." (PMID 34318601, 2021). "The majority of mutations affecting FBN1 result in Marfan syndrome (MFS); one of the most common human connective tissue disorders affecting the cardiovascular, skeletal and ocular systems." (PMID 33735269, 2021). "Marfan syndrome (MFS) is an autosomal dominant connective tissue disorder caused by a pathogenic variant in FBN1 and occurs de novo in a quarter of patients." (PMID 33034422, 2021). "Marfan syndrome (MFS) is a dominant autosomal disorder caused by mutations in the Fibrillin-1 (FBN1) gene, which results in a connective tissue defect." (PMID 34895303, 2021). "Trio-based analyses on familial cases identified a novel nonsense variant in FBN1, the gene implicated in Marfan syndrome (MFS; MIM#154700) and many monogenic diseases with scoliosis and spinal dysplasia." (PMID 31827250, 2020). "Marfan syndrome (MFS) is a heritable disorder of connective tissue, caused by mutations in the fibrillin-1 gene." (PMID 32616814, 2020). "Moreover regarding FBN1-dominant-negative Marfan syndrome, our finding that allele-dependent DNA methylation correlated with mRNA expression suggests that DNA hypomethylation of the mutant dominant-negative allele could exaggerate Marfan symptoms." (PMID 32210272, 2020). "Marfan syndrome (MFS) is an autosomal dominant disease caused by a mutation of heterozygous fibrillin-1 (FBN1) and presents cardiovascular symptoms and skeletal abnormalities." (PMID 32296011, 2020). "Patients with Marfan syndrome (MFS), a connective tissue disorder caused by pathogenic variants in the gene encoding the extracellular matrix protein fibrillin-1, have an increased prevalence of primary cardiomyopathy, arrhythmias, and sudden cardiac death." (PMID 32987703, 2020). "Marfan syndrome (MFS) (OMIM #000138) is an autosomal dominant hereditary connective tissue disease typically involving the Fibrillin‐1 (FBN1) mutations." (PMID 31830381, 2020). "We characterize a large Italian family presenting with Marfan syndrome (MFS), where the same NM_000138.4:c.6872-1G > T splice site mutation in the FBN1 gene was detected in 37 affected individuals with different pathological phenotypes." (PMID 32884772, 2020). "Marfan syndrome (MFS), caused by mutations in FBN1, is the commonest and best studied genetic disease resulting in TAAD." (PMID 33195187, 2020). "Marfan syndrome (MFS) is a connective tissue disease caused by mutations in the FBN1 gene, leading to alterations in the extracellular matrix microfibril assembly and the early formation of thoracic aorta aneurysms (TAAs)." (PMID 32961817, 2020). "Finally, we note the unusual result of normal RTPCR on a patient with Marfan syndrome and a de novo FBN1 (NM_000138.4:c.6872-1G>A) variant, which suggests that the effect of splicing may be tissue-specific." (PMID 32552793, 2020). "Mutations in the FBN1 (fibrillin-1) gene may be diagnostic of Marfan syndrome." (PMID 32883240, 2020). "Marfan syndrome (MFS) is caused by mutations in FBN1 (fibrillin-1), an extracellular matrix (ECM) component, which is modified post-translationally by glycosylation." (PMID 31315432, 2019). "Marfan syndrome (MFS) is a rare hereditary connective tissue disorder caused by a mutation in the FBN1 gene." (PMID 31620888, 2019). "Marfan syndrome (MFS) is a systemic multicomponent disease caused by mutations in the Fbn1 gene, which codes for the elastic microfibril protein fibrillin-1." (PMID 29765495, 2018).
Marfan syndrome (continued). "Marfan syndrome (MFS) is a pleiotropic genetic disease involving the cardiovascular system where a fibrillin-1 mutation is present." (PMID 29483877, 2018). "Marfan syndrome (MFS) is an autosomal dominant connective tissue disorder caused by mutations in the FBN1 gene." (PMID 30286810, 2018). "Marfan syndrome (MFS) is an autosomal dominantly inherited connective tissue disorder, mostly caused by mutations in the fibrillin-1 (FBN1) gene." (PMID 30003093, 2018). "Different mutations in the FBN1 gene lead to a wide range of diseases, such as Marfan syndrome (MFS), Weill–Marchesani syndrome, acromelic dysplasias, stiff skin syndrome and Marfanoid-progeroid-lipodystrophy (MPL) syndrome." (PMID 29666143, 2018). "Marfan syndrome (MFS), an autosomal dominant disorder of connective tissue caused by mutations in the fibrillin‐1 gene, FBN1, (OMIM *134797) is a potentially life‐threatening syndrome." (PMID 30393980, 2018). "Mutations in fibrillin-1 cause Marfan Syndrome (MFS) and related disorders from dysregulated TGF-β activity." (PMID 29312958, 2017). "With a prevalence of 1 in 10,000 individuals Marfan’s syndrome, an autosomal dominant disorder first clinically described in 1896 by Antonin-Bernard Marfan and genetically confirmed in the early 1990s, is caused by a mutation of the fibrillin-1 gene (FBN1), which maps to chromosome 5q21.1." (PMID 28715511, 2017). "Mutations in FBN1 result in multisystem abnormalities of connective tissues, most frequently manifesting as Marfan syndrome (MFS) in humans (MIM 154700)." (PMID 27386756, 2016). "Marfan syndrome (MFS) is caused by mutations in the FBN1 gene, leading to deficiency (haploinsufficient {HI} mutations) or malformation (dominant-negative {DN} mutations) of the fibrillin-1 protein, ultimately leading to aortic dilatation and dissection." (PMID 27704402, 2016). "The disease Marfan syndrome (MFS), a connective tissue disorder, is caused by a mutation in the Fibrillin-1 gene." (PMID 27110824, 2016). "Marfan syndrome (MFS) is a genetic disease caused by a mutation in the fibrillin-1 gene, which controls a component of connective tissue." (PMID 27249938, 2016). "Successful examples of iPSCs modeling skeletal genetic diseases have been reported for Marfan syndrome (MFS), an autosomal dominant disorder of connective tissue caused by mutations in the gene coding for Fibrillin-1 (FBN-1)." (PMID 26805822, 2016). "Targeting of FBN1 or the fibrillin-1 protein may provide a therapeutic avenue for conditions where there is a deficiency of adipose tissue (such as Marfan syndrome and lipodystrophy) and for obesity and type II diabetes, responsible for a major health burden in today's world." (PMID 27386756, 2016). "Marfan syndrome (MFS) is a heritable disorder of connective tissue resulting from pathogenic variants of the fibrillin-1 gene (FBN1)." (PMID 27138491, 2016). "Mutations in FBN1, encoding fibrillin-1 cause Marfan syndrome (MFS; OMIM #154700) and other heritable connective tissue disorders, referred to as fibrillinopathies." (PMID 26684006, 2015). "In asymptomatic Marfan syndrome (MFS) patients we evaluated the relationship between the types of fibrillin-1 (FBN1) gene mutation and possible altered left ventricular (LV) function as assessed by three-dimensional speckle tracking echocardiography (3D-STE)." (PMID 25901601, 2015). "FBN1 mutations typically cause Marfan syndrome (MFS, incidence 2-3 in 10,000), a serious connective tissue disorder affecting the cardiovascular and musculoskeletal systems, the eyes and the lungs." (PMID 25762570, 2015). "The majority of mutations affecting the human fibrillin-1 gene, FBN1, result in Marfan syndrome (MFS), a common connective tissue disorder characterised by tall stature, ocular and cardiovascular defects." (PMID 25979247, 2015).